GBP2 (guanylate binding protein 2)
Diseases named in the same sentence as GBP2 in open-access papers (continued):
Sharing a sentence is not in itself a finding about the gene and the disease.
endometriosis (1 paper, 2025). The growth of functional endometrial tissue in anatomic sites outside the uterine body. "Collectively, these data present Lifitegrast as a previously unappreciated intervention for endometriosis treatment and identify GBP2 and HCK as novel druggable targets in endometriosis treatment." (PMID 39666559, 2025). "In subcutaneous and intraperitoneal endometriosis mouse models, siRNAs targeting GBP2 and HCK notably reduced lesion volume and weight, with decreased proliferation and increased apoptosis within lesions." (PMID 39666559, 2025). "Thus, these collective results support the possible role of GBP2 in inducing immune dysregulation during endometriosis." (PMID 39666559, 2025). "Among the Omics scores, GBP2 and HCK showed predominant performance (scored over 0.7) in the “Network Neighbors”, “Causal Inference”, and “Expression” models, signifying their potential as novel therapeutic targets for the treatment of endometriosis." (PMID 39666559, 2025). "Dysregulated pathway analysis was performed to predict the potential functions of GBP2 and HCK in the endometriosis pathogenesis." (PMID 39666559, 2025). "In conclusion, this study uncovers the roles of two AI‐derived novel druggable targets, GBP2 and HCK, in endometriosis, whose inhibition delayed disease progression in multiple preclinical models." (PMID 39666559, 2025). "To evaluate GBP2 and HCK function in vivo, we performed independent siRNA knockdown of both targets in subcutaneous and intraperitoneal endometriosis mouse models." (PMID 39666559, 2025). "Knockdowns of GBP2 and HCK offered therapeutic effects on endometriosis by reducing proliferation and increasing apoptosis of the endometriotic cells." (PMID 39666559, 2025). "Consistent upregulations of GBP2 and HCK were observed at mRNA and protein levels in endometriotic samples, supporting their potential roles in driving endometriosis." (PMID 39666559, 2025). "Identifying GBP2 and HCK as novel therapeutic targets highlights that specific immune‐mediated mechanisms drive endometriosis, bringing our attention to the immunological aspects of the disease and paving the way for more targeted, effective treatment strategies." (PMID 39666559, 2025). "Using an artificial intelligence (AI)‐driven target discovery platform, two unreported therapeutic targets, guanylate‐binding protein 2 (GBP2) and hematopoietic cell kinase (HCK) are identified, along with a drug repurposing target, integrin beta 2 (ITGB2) for the treatment of endometriosis." (PMID 39666559, 2025). "With no previous study in endometriosis and scarce publications in other immune indications, GBP2 emerged as a novel target in endometriosis." (PMID 39666559, 2025). "We identified GBP2 and HCK as previously unappreciated therapeutic targets for endometriosis ii." (PMID 39666559, 2025). "These collective data demonstrate that GBP2 and HCK inhibition independently attenuated endometriosis pathology through suppression of cell proliferation and activation of apoptosis, highlighting the potential of these therapeutic interventions for treating endometriosis." (PMID 39666559, 2025). "Modulating GBP2 and HCK‐mediated processes, such as macrophage polarization, caspase‐dependent apoptosis, and natural killer cell function, may represent a complementary approach to existing endometriosis treatments, which primarily focus on hormonal or surgical strategies." (PMID 39666559, 2025). "Identifying GBP2 and HCK as targets without prior text‐based evidence in endometriosis studies highlights the power of our AI‐driven approach in uncovering previously unexplored mechanisms." (PMID 39666559, 2025). "Based on the aggregated scores from the 13 Omics models, GBP2 (Guanylate Binding Protein 2) and HCK (Hemopoietic Cell Kinase) attained the highest rankings as targets for endometriosis, without prior text‐based evidence from endometriosis studies." (PMID 39666559, 2025).
endometriosis (continued). "The expression of GBP2, HCK, and ITGB2 in matched eutopic endometrium and endometriosis lesions was not explored due to sample constraints." (PMID 39666559, 2025).
endotoxemia (1 paper, 2018). "However, deletion of GBP2 only slightly inhibited the release of IL-1α and IL-1β in endotoxemia." (PMID 30587103, 2018). "Accordingly, GBP2 deficiency failed to significantly reduced lethality in endotoxemia." (PMID 30587103, 2018). "Interestingly, we found that GBP2 deficiency fails to significantly inhibit caspase-11-dependent immune responses in endotoxemia; whereas genetic deletion of GBP1, GBP2, GBP3, GBP5 and GBP7 simultaneously blocked endotoxemia-induced caspase-11 activation." (PMID 30587103, 2018).
esophageal cancer (1 paper, 2014). A primary or metastatic malignant neoplasm involving the esophagus.
gastric cancer (1 paper, 2023). A primary or metastatic malignant neoplasm involving the stomach. "Taken together, GBP2 is positively associated with immune response in gastric cancer." (PMID 37784054, 2023). "This study uncovers that GBP2 expression is associated with the immuno-hot TMIE in gastric cancer and could predict the immunotherapeutic responses." (PMID 37784054, 2023). "We found that GBP2 was highly expressed in gastric cancer and associated with poor prognosis." (PMID 37784054, 2023). "GBP2 was highly expressed in tumor tissues and associated with poor prognosis in gastric cancer." (PMID 37784054, 2023). "In addition, GBP2 was associated with immune-hot TIME in gastric cancer." (PMID 37784054, 2023). "Although the role of GBP2 in cancer has been preliminarily explored, it is unclear how this protein interacts with tumor immunity in gastric cancer." (PMID 37784054, 2023). "In the current, we first analyzed the expression and immuno-correlations of GBP2 in gastric cancer and expand its immuno-related role in pan-cancer." (PMID 37784054, 2023). "A majority of chemokines, receptors, major histocompatibility complex (MHC) molecules, immunoinhibitors, and immunostimulators were notably correlated with GBP2 in gastric cancer." (PMID 37784054, 2023). "Totally, GBP2 is positively correlated with immunotherapeutic biomarkers and responses in gastric cancer." (PMID 37784054, 2023). "The expression, prognostic value, immune-correlations of GBP2 in gastric cancer was explored in multiple public and in-house cohorts." (PMID 37784054, 2023). "Considering that GBP2 was associated with multiple immune-related processes, we next explored the precise immunological role of GBP2 in gastric cancer." (PMID 37784054, 2023). "More immediately, GBP2 was overexpressed in gastric cancer tumors with the well immunotherapeutic response." (PMID 37784054, 2023). "In this research, we conducted comprehensive analysis of the immuno-correlation of GBP2 in gastric cancer." (PMID 37784054, 2023). "Overall, GBP2 is significantly upregulated in gastric cancer and correlated with poor prognosis." (PMID 37784054, 2023). "Overall, this study summarized the immuno-correlations of GBP2 in gastric cancer and pan-cancer, and GBP2 could be a novel biomarker for the predication of immunotherapeutic efficacy in most cancers." (PMID 37784054, 2023). "Our results showed that GBP2 could detect immuno-hot tumors in gastric cancer and was connected to an inflamed TIME." (PMID 37784054, 2023). "First of all, we examined the expression of GBP2 in gastric cancer." (PMID 37784054, 2023). "Similarly, GBP2 was also correlated with multiple immunotherapy biomarkers and the well response to immunotherapy in gastric cancer." (PMID 37784054, 2023). "In addition to gastric cancer, GBP2 was expected to be an indicator of high immunogenicity in most cancer types." (PMID 37784054, 2023). "However, there is still no definite evidence that GBP2 is related to immunotherapy in gastric cancer." (PMID 37784054, 2023).
hepatoma (1 paper, 2010). "Similarly, IL-27 has antiviral activity in hepatoma cells and can induce the expression of IRF-1, guanylate binding protein 2 and MxA proteins that are involved in the antiviral response." (PMID 20719000, 2010).
idiopathic myelofibrosis (1 paper, 2022). "There was another study showing that GBP2 overexpression suppressed the erythroid differentiation and increased the level of matrix metalloproteinase-9 in TF-1 cells, which was also found to be increased in patients with idiopathic myelofibrosis." (PMID 36061178, 2022).
insulinoma (1 paper, 2025). "LPS also does not activate NF-κB in C57BL/6 islets as assessed by IκBα degradation 30 min after LPS stimulation, nor does it stimulate Nos2, Gbp2, or Gbp5 expression by rat insulinoma INS832/13 cells." (PMID 41093076, 2025).
kidney cancer (1 paper, 2022). Primary or metastatic malignant neoplasm involving the kidney. "In addition, the expression of GBP2 was always significantly elevated in kidney cancer cell lines (769-P, Caki-2, and ACHN) compared to the normal human renal tubular epithelial HK-2 cells." (PMID 35356208, 2022).
leprosy (1 paper, 2019). Leprosy is a chronic infectious disease affecting primarily the skin and peripheral nervous system. "GBP1, GBP2 and GBP5 are specific to the RR signature in comparison to the other clinical forms of leprosy." (PMID 31600201, 2019).
lung disease (1 paper, 2021). "By specific lung cell isolation, several interferon-related and autoimmune genes were disproportionately expressed among CIA and CIA+ODE (e.g. Oasl1, Oas2, Ifit3, Gbp2, Ifi44, and Zbp1), corresponding to RA and RA-associated lung disease." (PMID 33577605, 2021).
malignant glioma (1 paper, 2022). A grade III or grade IV glioma arising from the central nervous system. "Single-cell analysis illustrated the high expression of GBP2 in malignant glioma cells showed the high antigen presentation capability, which were confirmed by real-time polymerase chain reaction (qRT-PCR) data." (PMID 36186425, 2022).
migraine (1 paper, 2025). "In migraine without aura, a rare nonsynonymous mutation in GBP2 (A907G) was identified in patients and absent in controls, suggesting a potential role in vasomotor dysfunction and migraine pathogenesis." (PMID 41181145, 2025).
mycobacterial infections (1 paper, 2022). "Of 15 prioritized in this study genes, four genes, namely GBP2, HEATR3, PPP1R9B and KDM6A, exhibited an elevated transcriptional level in whole blood, spleen or EBV-transformed lymphocytes, thus lending additional support to their role in increasing susceptibility to mycobacterial infections." (PMID 36338958, 2022).
myelofibrosis (1 paper, 2022). A partial or complete replacement of the bone marrow stroma by fibrous tissue. "Additionally, the four genes (OAS1, IFITM3, GBP1, and GBP2) we identified in this study might have the potential to be auxiliary diagnostic and predictive indicators of myelofibrosis, but further investigations are still necessary in the future." (PMID 36061178, 2022). "The results showed high AUC values of the four genes (OAS1, IFITM3, GBP1, and GBP2) when distinguishing JAK2V617F+ myelofibrosis from JAK2V617F+ PV or ET." (PMID 36061178, 2022). "The external datasets validated the upregulation of four interferon-related genes (OAS1, IFITM3, GBP1, and GBP2) in JAK2V617F+ myelofibrosis." (PMID 36061178, 2022). "Furthermore, we identified four potentially important genes (OAS1, IFITM3, GBP1, and GBP2) that were upregulated uniquely in myelofibrosis." (PMID 36061178, 2022). "Therefore, these four genes (OAS1, IFITM3, GBP1, and GBP2), especially OAS1, might possess the potential to be novel auxiliary diagnostic and predictive indicators of myelofibrosis, but further research is still necessary in the future." (PMID 36061178, 2022). "Overall, the four interferon-stimulated genes (OAS1, IFITM3, GBP1, and GBP2) exclusively upregulated in myelofibrosis might not only provide important novel clues to the MPN field but also offer special insights into the effects of IFN signaling on the pathogenesis of myelofibrosis." (PMID 36061178, 2022).
neuroblastoma (1 paper, 2022). Neuroblastoma (NB) is the most common solid, extracranial childhood tumor. "We further validated our results in JEV infected human neuroblastoma SH-SY5Y cells, where we observed significantly enhanced transcript levels of Gbp1, Gbp2, Gbp4 & Gbp5." (PMID 35663470, 2022).
Obesity (1 paper, 2023). Accumulation of substantial excess body fat. "Based on previous studies reporting the role of IFN-γ in obesity and the correlation between Gbps and IFN-γ, the potential for Gbp2 to be involved in the regulatory mechanisms in NAFLD is plausible, although the detailed underlying mechanisms remain unknown." (PMID 36609599, 2023).
ocular hypertension (1 paper, 2024). Abnormally high intraocular pressure. "Gene expression of signature astrocyte reactivity markers (Gfap, Lcn2, Steap4, Gbp2, Serping1, and Fbln5) were significantly upregulated in response to ocular hypertension at 2, 4, and 8 weeks compared to that in normotensive controls." (PMID 38610040, 2024).
Pancytopenia (1 paper, 2017). An abnormal reduction in numbers of all blood cell types (red blood cells, white blood cells, and platelets). "Most of the genes from day 1 appeared 2-fold downregulated (e.g., CDCA7L or GBP2), but three were 3–5-fold upregulated (C11orf96, GLUL, TM4SF19) relative to H0 when developing a HARS without pancytopenia." (PMID 28236054, 2017).
Pleural effusion (1 paper, 2023). The presence of an excessive amount of fluid in the pleural cavity. "Among the top 10 genes, CARD-17, GBP2, and C1QB expressed in PF showed an above 80% accuracy rate in discriminating PlTB from other causes of pleural effusion." (PMID 38288122, 2023).
primary Sjögren’s syndrome (1 paper, 2025). "In primary Sjögren’s syndrome, GBP2 serves as a salivary biomarker that not only distinguishes patients from healthy controls but also differentiates primary Sjögren’s syndrome from systemic lupus erythematosus." (PMID 41181145, 2025).
renal carcinoma (1 paper, 2025). A carcinoma arising from the epithelium of the renal parenchyma or the renal pelvis. "GBP2 in renal carcinoma resists traditional immunotherapies, possibly via Stat1 pathways that bolster cell survival under immune pressure, driven by its homodimerization and cytokine interactions." (PMID 40564939, 2025).
Salmonella Infections (1 paper, 2024). Infections with bacteria of the genus SALMONELLA. "It is tempting to speculate that the loss of GBP2 led to the expansion of GBP4 in M. Myotis and E. fuscus since, in humans, upon Salmonella infection, GBP1 requires GBP2 and GBP4 to recruit caspase-4 to the surface of the bacteria." (PMID 38357541, 2024).
sporadic Creutzfeldt-Jakob disease (1 paper, 2022). A rare sporadic human prion disease characterized by rapidly progressive cognitive impairment in combination with variable neurologic signs and symptoms including myoclonus, visual or cerebellar problems, pyramidal or extrapyramidal features, or akinetic mutism. "Additionally, data from human patients with sporadic Creutzfeldt-Jakob Disease (sCJD) show that A1 astrocyte markers, such as GBP2, stratify to molecular subtypes in sCJD brains, which may account for the divergence of A1 astrocytic markers among molecular subtypes in these patients." (PMID 35351973, 2022).
triple-negative breast carcinoma (1 paper, 2025). An invasive breast carcinoma which is negative for expression of estrogen receptor (ER), progesterone receptor (PR), and human epidermal growth factor receptor 2 (HER2). "GBP2 enhances paclitaxel sensitivity in triple-negative breast cancer by promoting autophagy in combination with ATG2 and inhibiting the PI3K/AKT/mTOR pathway." (PMID 41007849, 2025).
ZIKV infection (1 paper, 2024). "A previous study identified GBP2/5, two GBP1-prenylation paralogs, to be upregulated upon ZIKV infection, thus leading to reduced viral replication through inhibition of the host protease furin." (PMID 38315728, 2024).
infection (56 papers, 2007 to 2025). The state of being infected such as from the introduction of a foreign agent such as serum, vaccine, antigenic substance or organism. "During BM-MoDCs infection with T. gondii, GBP2 forms a tight ring around the PV containing T. gondii and iNOS is closely associated with GBP2+ PVs." (PMID 40631203, 2025). "To this end, we infected WT, Gbp1–/–, Gbp2–/–, Gbp3–/–, Gbp5–/–, and Aim2–/– mice with F. novicida and monitored their susceptibility to infection." (PMID 35906252, 2022). "During infection of exogenous pathogenic microorganism, many types of murine Gbps and human Gbp2 and Gbp5 can trigger the host cells’ pyroptosis by activating inflammasome complex containing caspase-1 or caspase-4." (PMID 32731337, 2020). "Infection of Atg5- and Atg3-deficient cells show decreased accumulation of immunity-related GTPase family member b10 (Irgb10) and guanylate-binding protein 2 (Gbp2) at T. gondii PVM." (PMID 28955329, 2017). "GFP loss on GBP2+ vacuoles were observed from 1 h 20 min to 19 h post-infection." (PMID 38538595, 2024). "Consistent with our hypothesis, intranasal infection of mice with B. thailandensis revealed that Gbp2−/−, Gbp5−/−, and GbpChr3-KO mice were highly susceptible to infection." (PMID 32150572, 2020). "Among the genes positively regulated by IRF1 signalling and directly bound by IRF1, we found the already known targets, guanylate-binding protein 2 (Gbp2) and Gbp5 (refs 50, 51), which contribute to clearance of infection as well as Th1-associated genes, including Il12rb1 (refs 1, 36)." (PMID 28497800, 2017). "We chose to analyze GBP2 protein based on our transcriptomic data where GBP2 is the most highly elevated during infection with L. major compared to the other GBPs." (PMID 40631203, 2025). "During infection of untreated macrophages, we observed similar GBP2 expression compared to uninfected BMDMs cultured in media alone." (PMID 40631203, 2025). "In infection with Moraxella catarrhalis, GBP2 acts as the dominant GBP driving inflammasome activation." (PMID 41181145, 2025). "The mechanism of GBP2 involving carcinogenesis includes regulating development and metastasis, immune surveillance and immunotherapy, chemoresistance, immunity against infections, apoptosis, and treatment." (PMID 41181145, 2025). "It has been shown that dendritic cells derived from the blood of healthy human donors expressed more GBP1 and GBP2 after infection with L. major promastigotes, whereas dendritic cells infected with L. donovani expressed more GBP1." (PMID 40100809, 2025). "GBP2 co-localized with 40% of T. gondii vacuoles by two hours post-infection in BM-MoDCs treated with IFNγ or IFNγ and Pam3CSK4, but not in unstimulated or Pam3CSK4-only stimulated conditions." (PMID 38538595, 2024). "We analyzed the impacts of GBP2 on the infection efficiency mediated by MLV Envs of different strains of ecotropic Moloney, polytropic Friend, amphotropic, and xenotropic MLV-related (XMRV) viruses." (PMID 39337476, 2024). "The findings revealed a significant increase in viral genomic copies and viral protein level when GBP2 was knocked down during ECTV-EGFP infection." (PMID 37958732, 2023). "Our results in this study showed that the protein levels of GBP2 were upregulated in sh-Con cells, with a higher upregulation level observed after infection with ECTV-EGFP-ΔPAPL compared to ECTV-EGFP infection." (PMID 37958732, 2023). "A significant increase in GBP2 mRNA levels in cells was observed, peaking at 12 h post-infection (hpi), showing an increase of over 180-fold." (PMID 37764102, 2023). "In contrast, OC43 infection induced all IFN-inducible genes tested at 2 days after infection, and the expression levels were significantly higher than control at 4 days except for GBP2 and STAT2." (PMID 37197656, 2023).